EDIL3 (EGF like and discoidin domains 3)
Diseases named in the same sentence as EDIL3 in open-access papers (continued):
Sharing a sentence is not in itself a finding about the gene and the disease.
tumor (43 papers, 2009 to 2026). "EDIL3, an extracellular matrix protein, has been linked to angiogenesis and metastasis, making it a key player in tumor invasion." (PMID 40151638, 2025). "EDIL3 expression was positively associated with numerous tumor-infiltrating immune cells and their biomarkers." (PMID 37576496, 2023). "EDIL3 was positively associated with most tumor-infiltrating lymphocytes (TILs), including mast cells, eosinophils, macrophages, memory B cells, NK cells, and Th2 cells." (PMID 37576496, 2023). "Positive expression of EDIL3 was associated with deeper tumor depth (P = 0.041), lymph node metastasis (P = 0.002), and advanced pTNM stage (P = 0.023)." (PMID 37576496, 2023). "In contrast, EDIL3 expression was inversely associated with tumor purity ( r = − 0.129, P = 1.17e−02)." (PMID 37576496, 2023). "High level of EDIL3 protein is much more commonly in patients with larger tumor or portal vein tumor thrombus (PVTT) formation, associated with poor prognosis." (PMID 25273699, 2014). "Overall, these results demonstrated that EDIL3 was closely associated with tumor progression and may serve as a potential prognostic marker for GC." (PMID 37576496, 2023). "Recently, reports have shown that EDIL3 was abnormally expressed in various tumors and tightly related to tumor initiation and progression." (PMID 37576496, 2023). "To investigate EDIL3 expression patterns in different tumor types, we used the online GEPIA database." (PMID 37576496, 2023). "The results indicated that EDIL3 expression had significant positive correlations with most immune gene markers and these correlations barely changed after tumor purity correction." (PMID 37576496, 2023). "All six proteins are differentially expressed in malignant vs. healthy tissue in CRC (FBLN1, MMP3, ACTN4, THBS1, EDIL3) or other tumour entities (QSOX1)." (PMID 33802764, 2021). "As we aimed to identify potential biomarkers for diagnostic purposes in vitro and to assess these markers in vivo, we investigated the QSOX1, THBS1 and EDIL3 levels in blood plasma obtained from patients 1–3 prior to tumour resection." (PMID 33802764, 2021). "The mRNA level of EDIL3 in tumor was correlated with the level of EDIL3 protein expression using immunohistochemistry." (PMID 28819306, 2017). "Secondly, the mRNA level of EDIL3 in tumor was correlated with the level of EDIL3 protein expression using immunohistochemistry." (PMID 28819306, 2017). "Overexpressed EDIL3 can reduce tumor cell apoptosis and increase tumor vascularization, thus promoting tumor growth." (PMID 26735172, 2016). "The capabilities of EDIL3 in tumor vascularization make it a candidate target for cancer anti-angiogenic therapy and also other diseases characterized by abnormal vascularization." (PMID 26735172, 2016). "Collectively, these data indicate that EDIL3 promotes anoikis resistance and anchorage-independent growth and this prerequisite facilitates tumor progression." (PMID 26735172, 2016). "Taken together, our data, as a proof of principle, demonstrate the promotive effect of EDIL3 on tumor growth in PDAC." (PMID 26735172, 2016). "Meanwhile, treatment with recombinant EDIL3 protein markedly promoted anoikis resistance and anchorage independent tumor growth." (PMID 26735172, 2016). "Treatment with a specific inhibitor of Bcl-2, ABT-199 (also known as Venetoclax) at 1 μM, EDIL3-mediated anoikis resistance and anchorage-independent tumor growth were completely blocked." (PMID 26735172, 2016). "The results clearly indicate that the size of tumor formed in SMMC-7721 with EDIL3-overexpression is significantly larger than the control cells in the 2–4 week after subcutaneous implantation." (PMID 25273699, 2014). "The result revealed that EDIL3 stain was very strong in all of the PVTT samples (6/6) as well as microscopic tumor thrombus, and this was validated by western blot." (PMID 25273699, 2014).
tumor (continued). "We observed approximately 72% (57/202) of patients were EDIL3-positive, and high levels of EDIL3 positivity was significantly associated with adverse clinicopathological parameters of HCC, including tumor size, PVTT formation, and TNM stage." (PMID 25273699, 2014). "EDIL3, known for its involvement in endothelial cell adhesion, may facilitate tumor angiogenesis, while SQLE, an enzyme in the cholesterol biosynthesis pathway, could support membrane biogenesis in rapidly proliferating tumor cells." (PMID 39015570, 2024). "The exact function of EDIL3 in the tumor-immune microenvironment needs further investigation." (PMID 37576496, 2023). "Additionally, we utilized TIMER to examine the correlation between EDIL3 expression and the infiltration of six major types of immune cells and tumor purity." (PMID 37576496, 2023). "Researches showed that EDIL3 promoted tumours growth through promoted angiogenesis." (PMID 36065978, 2022). "However, EDIL3 expression can be re‐initiated during ischemia and is upregulated in tumour vascular tissues." (PMID 36065978, 2022). "To summarise, we were able to identify activation status-related proteins in fibroblast-derived EXOs by using mass spectrometry and validated three of the four selected candidate proteins (QSOX1, THBS1 and EDIL3) related to malignant transformation and tumour progression." (PMID 33802764, 2021). "These proteins (THBS1, FBLN1, EDIL3, QSOX1, ACTN4, MMP3) also displayed differential mRNA expression in CRC compared to healthy intestine in the CRC TCGA dataset, and are implicated in tumour growth and metastasis regulation." (PMID 33802764, 2021). "Taken together, these data above suggest that up-regulated EDIL3 predicts poor prognosis and might contribute to tumor progression in PDAC." (PMID 26735172, 2016). "We continued to investigate the effect of EDIL3 on tumor cell invasion and anoikis." (PMID 25273699, 2014). "Indeed, all of the fresh PVTT samples in our study exhibited a very high level of EDIL3 protein, so it is highly possible that tumor cells bring this protective protein when leaving primary lesion, thus assisting PVTT formation." (PMID 25273699, 2014). "Moreover, the accumulation of tumor-derived EDIL3 in the microenvironment promotes anoikis resistance and anchorage independent growth advantage through the activation of integrin signal pathways." (PMID 25273699, 2014). "Epidermal Growth Factor-like repeats and Discoidin I-Like Domains 3 (EDIL3), an extracellular matrix (ECM) protein associated with vascular morphogenesis and remodeling, is commonly upregulated in multiple types of human cancers and correlates with tumor progression." (PMID 26735172, 2016). "Further bioinformatics analysis of miR-24-1-5p targets, including CD34, ACACA, TPM3, UFC1, EDIL3, and CHEK1, reinforces their role in tumor immune cell infiltration and the transformation of the tumor microenvironment." (PMID 38840234, 2024). "Some DEGs like FREM2, ANXA2 and GPC4 revealed common enrichment in LE/IT tumor regions across GBM patient samples compared to the overall downregulation of the OPC/OL marker MBP, the neural marker NTRK2, and the ECM glycoprotein EDIL3." (PMID 41366031, 2025). "The mRNA level of EDIL3 was markedly increased in 13 (65.0%) tumor tissues compared with adjacent non-neoplastic tissues (P = 0.0401)." (PMID 37576496, 2023). "To validate these results, we applied qRT-PCR and Western blot assay to analyze the mRNA and protein levels of EDIL3 in 20 pairs of GC tumor tissues and adjacent non-neoplastic tissues." (PMID 37576496, 2023). "EDIL3 expression did not correlate with gender, age, tumor size, or tumor differentiation (P > 0.05)." (PMID 37576496, 2023).
tumor (continued). "The expression level of EDIL-3 is much higher in BC patients than healthy individuals, but not in the tumor cell line or their exosomes from conditioned media." (PMID 35787656, 2022). "The effects of tumor related genes (SOX4 and EDIL3) in IgAN need further clarification." (PMID 33936064, 2021). "The mRNA level in tumors positive for EDIL3 immunohistochemistry was higher than that in tumor-free control lung samples (p = 0.06) and tumors without EDIL3 immunohistochemical positivity (p = 0.057)." (PMID 28819306, 2017). "Our results also identified the protein expression of EDIL3 on some macrophages and lymphocyte of tumor-free control samples however pneumocytes, bronchial epithelium and endothelial cells were negative for EDIL3 immunohistochemistry." (PMID 28819306, 2017). "In addition, CD34, EDIL3, and TPM3 were positively correlated with signaling pathways related to tumor immune response, invasion, and metastasis, particularly the IL6/JAK/STAT3, inflammatory response, TNF-α signaling via NF-kB, and epithelial-mesenchymal transition." (PMID 38840234, 2024). "Knockdown of EDIL3 showed no significant influence on cell viability, migration, invasion and starvation-induced apoptosis, but compromised anoikis resistance and anchorage independent tumor growth of PDAC cells." (PMID 26735172, 2016). "This may explained by that these normal pancreas tissues were mainly non-tumor tissues derived from patients with PDAC and the tumor microenvironment of PDAC was likely to turn on the expression of EDIL3 in adjacent normal tissues." (PMID 26735172, 2016). "Similarly, recombinant EDIL3 protein had no obvious implications on cell proliferation, migration, invasion and starvation-induced apoptosis, whereas inhibited anoikis and promoted anchorage-independent tumor growth in a dose-dependent manner." (PMID 26735172, 2016).
cancer (37 papers, 2009 to 2025). A tumor composed of atypical neoplastic, often pleomorphic cells that invade other tissues. "The EVs of the two complex carcinoma cell lines shared 487 over-represented proteins, mostly associated with angiogenesis, cell migration, adhesion and motility (ECM1, EDIL3, VEGFC)." (PMID 39462388, 2024). "Until recently, the mechanism of abnormal expression of EDIL3 in human cancer was not fully understood." (PMID 37576496, 2023). "As a secreted ECM protein, EDIL3 is involved in multiple processes in cancer occurrence and development." (PMID 37576496, 2023). "Recently, the role of EDIL3 in cancer occurrence and development has attracted a great deal of attention." (PMID 37576496, 2023). "The blockade of the interaction of secreted EDIL3 with the integrin αVβ3 by cilengitide restored sensitivity to paclitaxel, and reverted the mesenchymal phenotype in paclitaxel-resistant cancer cells." (PMID 33014430, 2020). "Overexpression of EDIL3 can contribute to carcinogenesis by reducing apoptosis in cancer cells and promoting cancer vascularization." (PMID 28819306, 2017). "A total of 24 paraffin blocks consisted of 8 of normal, 8 of EDIL3 low expression cancer and 8 of EDIL3 high expression were evaluated." (PMID 28819306, 2017). "The role of EDIL3 in cancer is also revealed in several malignancies, albeit in observational level." (PMID 25273699, 2014). "Taken together, these results indicate that EDIL3, especially secreted by cancer cells in our current study, is effective in protecting them from anoikis after suspension, thus supporting anchorage independent growth." (PMID 25273699, 2014). "EDIL3 treatment reduced the Caspase3/7 activity and increased the viability in cancer suspended in poly-hema coated dishes for long to 72 h." (PMID 25273699, 2014). "Our study detected the abnormal DNA methylation of EDIL3 genes in various cancers." (PMID 37576496, 2023). "The results of SMART analysis showed that the methylation status of EDIL3 genes was different in different cancers, suggesting that it may play distinct roles in different tumors." (PMID 37576496, 2023). "In total, nine inflammation and cancer-associated DEGs were selected to show their changed expression patterns, comprising four up-DEGs (ADM, FSTL3, SPDEF, and SPNS2) and five down-DEGs (TACSTD2, CCL2, EDIL3, FAM20C, and OLFML2A)." (PMID 37953789, 2023). "In addition, paclitaxel-sensitive cancer cells overexpressing-EDIL3 or cultured in CM were more resistant to this drug, and showed the induction of EMT." (PMID 33014430, 2020). "So, we decided to investigate whether the blockade of the interaction between EDIL3 and integrin αVβ3 with cilengitide had an effect on the paclitaxel response of cancer cells." (PMID 33014430, 2020). "Moreover, ALX4, PDLIM1, CAP2 and EDIL3 have also been found to be correlated with the prognosis of cancer." (PMID 28178989, 2017). "Several attempts have been made to explore the therapeutic effect of EDIL3 in cancer." (PMID 28819306, 2017). "By overexpressing EDIL3 or recombinant EDIL3 treatment, we observed that secreted EDIL3 reduced the likelihood of anoikis in cancer cells and promoted anchorage-independent growth, both of which are indispensable for HCC spreading and PVTT formation, whereas do not affect proliferation or invasion." (PMID 25273699, 2014). "Therefore, EDIL3 may be a good candidate target for developing novel cancer anti-angiogenic therapies." (PMID 28819306, 2017). "Notably, co-stain of EDIL3 and endothelium marker CD31 in HCC samples showed EDIL3 is not only stained with endothelium marker, but also widely and diffusively located in cancer cells clusters, suggesting that cancer cells becomes an important sources of EDIL3 besides endothelium." (PMID 25273699, 2014).
cancer (continued). "Compared to primary cancer samples, genes such as GLYATL2, EDIL3, MEG3, FABP4, ASCL1, GRP, and WDFY4 were highly upregulated in CRPC, with statistically significant differences underscoring their potential roles in driving the castration-resistant phenotype." (PMID 40165961, 2025). "In contrast, CBX3, CHN1, SULF1 and VDAC1 were significantly elevated in SKCM compared to HD samples, while EDIL3 and PALLD demonstrated significantly lower expression levels in the cancer samples." (PMID 41350567, 2025). "Cilengitide blocks the EDIL3‐integrin αVβ3 interaction to restore sensitivity to Taxol and mitigates EMT in Taxol‐resistant cancer cells." (PMID 34766149, 2021). "EDIL3 and DDX43 were the most significantly upregulated genes in patients with high metastatic burden, whereas the cancer-testis (CT) antigens, such as MAGEA1, were found to show reduced expression in these patients." (PMID 32847064, 2020). "Blockade of EDIL3–integrin αVβ3 interaction by cilengitide restores sensitivity to paclitaxel and reverts EMT in paclitaxel-resistant cancer cells." (PMID 33014430, 2020). "Since EDIL3 is a regulator of EMT and both EDIL3 and EMT play important roles in the progression of cancer and acquisition of resistance to chemotherapy, we studied the expression of EDIL3 and its impact on paclitaxel resistance." (PMID 33014430, 2020). "Three selected proteins (QSOX1, THBS1 and EDIL3) were detected in CRC patient pEXOs and might be useful candidates in early cancer diagnostics engaging non-invasive liquid biopsy." (PMID 33802764, 2021). "In summary, EDIL3 may contribute to EMT and paclitaxel resistance through autocrine or paracrine signaling in cancer cells." (PMID 33014430, 2020). "Epidermal growth factor-like repeat and discoidin I-like domain-containing protein 3 (EDIL-3) and lysyl oxidase homolog 2 (LOXL2) were reported to facilitate cancer cell migration and pre-metastatic niche formation which were also down-regulated in the DET or DETD-35 responsive exosomes." (PMID 28706483, 2017). "Highly expressed transcripts in MCF-7/Twist cells include EDIL3, which has, so far, not been found to be involved in cancer development but is involved in immune system-dependent engulfment of apoptotic cells." (PMID 28086829, 2017). "To support the results of protein expression by immunohistochemistry in normal and cancer tissues, we performed real-time qRT PCR in normal, EDIL3 negative cancer and EDIL3 positive cancer respectively." (PMID 28819306, 2017). "Our study suggests that high levels of autocrine EDIL3 may contribute to a receptive microenvironment for the survival of detached HCC cells and may involve in cancer cell spreading." (PMID 25273699, 2014). "EDIL3 is abundantly expressed in HCC cells and secreted by cancer cells." (PMID 25273699, 2014). "Our study suggests that high levels of autocrine EDIL3 may contribute to a receptive microenvironment for the survival of HCC cells and therefore assist cancer cell progression, which lead to adverse clinical results." (PMID 25273699, 2014). "Moreover, EDIL3 may be involved in EMT and Taxol resistance in cancer cells through autocrine or paracrine signaling." (PMID 34766149, 2021). "The studies by Mineo and Beckham have regulation of the Src-family of proteins in common, as EDIL-3 is known to activate the FAK-Src-AKT pathway in hepatocellular carcinoma, which may contribute to the explanation for the relationship between cancer-derived exosomes and angiogenesis." (PMID 28796150, 2017).
infection (5 papers, 2013 to 2024). The state of being infected such as from the introduction of a foreign agent such as serum, vaccine, antigenic substance or organism. "Endothelial cells secrete EDIL3 to limit neutrophil recruitment to sites of infection and restrain the initiation of inflammation." (PMID 35360858, 2022).
adenocarcinoma (1 paper, 2017). A common cancer characterized by the presence of malignant glandular cells. "In adenocarcinoma patients, EDIL3 expression was significantly correlated with low e-cadherin expression (P < 0.001), high vimentin expression (P = 0.001), and increased microvessel density (P = 0.023)." (PMID 28819306, 2017). "In the multivariate analysis, EDIL3 expression was an independent prognostic marker of OS in adenocarcinoma patients (hazard ratio: 2.552, P = 0.004)." (PMID 28819306, 2017). "In the present study, EDIL3 expression was found to be correlated with microvessel density and poor outcome in adenocarcinoma cases." (PMID 28819306, 2017). "Among adenocarcinoma patients, EDIL3-positive patients had lower 5-year OS rates than did EDIL3-negative patients (51.9% vs. 70.7%, P = 0.014)." (PMID 28819306, 2017). "However, EDIL3 was not significantly (P > 0.05) associated with lymphovascular invasion, pathologic TNM stage, or smoking history in adenocarcinoma patients." (PMID 28819306, 2017).
EDIL3 also shares sentences with these, for which no sentence is quoted: Hypertension (5 papers); colorectal cancer (4); Obesity (4); atherosclerosis (3); cardiovascular disease (3); endothelial dysfunction (3); Insulin resistance (3); benign breast tumors (2); cardiac hypertrophy (2); coronary heart disease (2); emphysema (2); Lewis lung carcinoma (2); mesothelioma (2); metabolic disease (2); pancreatic adenocarcinoma (2); pancreatic ductal adenocarcinoma (2); peripheral arterial disease (2); pulmonary fibrosis (2); Type 2 Diabetes (2); acute lung injury (1); adrenal gland (1); age-related macular degeneration (1); allergic asthma (1); Alzheimer disease (1); ankylosing spondylitis (1); aortic aneurysm (1); Arthritis (1); asthma (1); autoimmune conditions (1); autoimmune disease (1).
A further 42 diseases each share a sentence with EDIL3 in 1 paper.